GLS (glutaminase)
Diseases named in the same sentence as GLS in open-access papers (continued):
Sharing a sentence is not in itself a finding about the gene and the disease.
cancer (continued). "Glutamine, an amino acid needed for protein synthesis and for cellular proliferation, is converted to glutamate by glutaminase, and the disruption of cancer metabolism through glutamine inhibition has been an attractive target for solid and hematological tumor therapies for many years." (PMID 37228498, 2023). "Our results thus indicated that purified glutaminase free L-ASNase from B. halotolerans ASN9 may be a promising anticancer enzyme for various cancers." (PMID 38015853, 2023). "However, the majority of cancer cell lines demonstrate upregulated glutaminolysis and dependence of cell growth on expression/activity of glutaminase." (PMID 36515528, 2023). "Notably, we found that GLS expression was significantly higher in ESCC tissues than in para-carcinoma tissues in all four datasets." (PMID 37665670, 2023). "Glutamine dependency has been targeted in several cancers, primarily by inhibiting glutaminase." (PMID 35110412, 2022). "Given that MYC, SLC1A5, and mTORC1 levels are higher in glutamine-addicted cancer cells, along with glutaminase levels, all of these can be exploited in future clinical studies as biomarkers to identify patients when assessing the potential effectiveness of glutaminolysis inhibitors." (PMID 36499623, 2022). "Consequently, cancer cells are forced to import more glutamine and activate glutaminase to fuel the TCA cycle and mitochondrial respiration leading to glutamine dependency." (PMID 36338517, 2022). "In concert with cancer metabolic switch for proliferating cells, the role of glutamine metabolism in the development of PH, especially glutaminase as a key enzyme in the initiation of glutamine hydrolysis pathway, has drawn great attention worldwide in recent years." (PMID 35310969, 2022). "GAC is the predominant glutaminase isoform expressed in cancer cells." (PMID 35008407, 2022). "Several studies have proposed different mechanisms by which GLS is regulated in cancer cells." (PMID 36139432, 2022). "Autophagy and glutaminase inhibitors might also be used to decrease mitochondrial metabolism in some cancers." (PMID 36358687, 2022). "Furthermore, glutamine and glutamate, the substrate and product of the glutaminase reaction, can serve as signaling molecules to regulate redox and bioenergetic pathways in cancer." (PMID 36818726, 2022). "Taken together, the use of GLS inhibitors in conjunction with other therapies may provide a viable strategy for the effective treatment of cancer." (PMID 36499623, 2022). "The activity of glutaminase (GLS) is significantly increased in cancer patients." (PMID 36523985, 2022). "However, some cuproptosis-associated genes, including MTF1, GLS, and CDKN2A, were positively associated with immune, stromal, and ESTIMATE scores, and the levels of immune and stromal cells were high across cancers, with low tumor purity." (PMID 36105090, 2022). "This will make it possible to stratify additional patient populations that are resistant to cancer treatment but could benefit from GLS inhibitor treatment in combination with other anti-cancer drugs." (PMID 36499623, 2022). "Indeed, after glutamine absorption by cancer cells, glutaminase converts it to glutamate, which enters the mitochondria or the cytoplasm to maintain the operational TCA cycle." (PMID 35912242, 2022). "Moreover, given the tumors’ addiction to glutamine, the inhibition of glutaminase with glutamine analogs has been proposed as a means of treating cancer." (PMID 35053485, 2022). "In preclinical models, glutaminase inhibition has suppressed cancer cell growth." (PMID 36005167, 2022). "Although glutaminase inhibition or anti-PD1 immunotherapy may be beneficial to this subset of cancer as monotherapy, their combination could lead to a contradictory effect." (PMID 36499623, 2022). "Furthermore, results from patient cancer tissues cultured in 13C6-glucose or 13C5,15N2-glutamine tracers provided clear evidence of selective activation of PC over glutaminase (GLS) in NSCLC." (PMID 35387341, 2022).
cancer (continued). "It has been reported that aberrant GLS expression promotes cancer cell proliferation." (PMID 36582227, 2022). "According to this research, these compounds might be used as glutaminase inhibitors in the fight against cancer." (PMID 36080453, 2022). "Even though these glutaminase inhibitors and Glu analogs introduced the possibility of targeting Glu addiction in PAH, dose-limiting toxicities associated with their usage, as observed in cancer, must be carefully considered." (PMID 33996951, 2021). "Targeting GLS has been explored and documented to be beneficial for cancer therapy." (PMID 34054545, 2021). "Elevated expression of GLS has been observed in several types of cancer." (PMID 34332338, 2021). "In line with this, it was shown that cancer cells with KEAP1 mutation and/or NRF2 hyperactivation exhibit increased glutamine dependency and enhanced sensitivity to glutamine deprivation or glutaminase inhibition, partly via high SLC7A11-mediated glutamate export in these cancer cells." (PMID 33000412, 2021). "This transcription factor may be an attractive target to control the GLS activity as a therapeutic strategy in cancers with a high dependency on glutamine." (PMID 33513833, 2021). "Indeed, environmental cystine availability increases glutamine anaplerosis through Cystine/glutamate transporter (xCT)/solute carrier family (SLC) 7A11 and enhances the efficacy of glutaminase inhibition in cancer cells." (PMID 33401771, 2021). "Therefore, the high reliance on glutamine of cancer cells makes targeting GLS to inhibit glutaminolysis a promising therapy option for human cancers including CRC." (PMID 34373753, 2021). "Elevated expression of GLS has been found in various cancers." (PMID 34373753, 2021). "Recently, valuable studies and bioinformatics analysis demonstrated that some emerged microRNAs (miRNAs) can efficiently control glutamine metabolism by targeting critical enzymes, such as glutaminase (GLS), which can provide an opportunity for regulating cancer development." (PMID 34233668, 2021). "This adaptive glutamine catabolism sensitizes cancer cells to glutaminase inhibition." (PMID 33673109, 2021). "However, it cannot be suppressed by a GLS inhibitor or GLS siRNA, or even chloroquine, indicating that CAFs autophagy induced by cancer cells lead to CAFs providing nutrition to cancer cells." (PMID 34503536, 2021). "Thus, targeting glutamine dependence through GLS inhibition has emerged as an attractive strategy for cancer treatment." (PMID 34354052, 2021). "Moreover, recent studies in other tumour types showed that GLS inhibition also sensitizes cancer cells to proteasome inhibitors due to the induction of ER stress and apoptosis, and to EGFR-targeted monoclonal antibodies by triggering apoptosis." (PMID 34572926, 2021). "Tumor metabolism has emerged as an attractive target for therapy development, and several drugs including metformin (mitochondrial respiration), enasidenib (mutated IDH2), l-asparaginase, devimistat (PDH/αKGDH), CB-839 (glutaminase inhibitor) are being used in various cancer trials." (PMID 34911956, 2021). "Moreover, the glutamine analogue (6-diazo-5-oxo-L-norleucine (DON))-containing prodrug JHU083 inhibits glutamine-metabolizing glutaminase in cancer cells." (PMID 33810170, 2021). "Importantly, in an orthotopic mouse model of ovarian carcinoma, co-targeting GS in CAFs and glutaminase in cancer cells effectively reduced tumor growth and metastasis, which underscores the significance of targeting the stromal cancer metabolic crosstalk." (PMID 34201298, 2021). "The chemical compound 5-(3-bromo-4-(dimethylamino)phenyl)-2,2-dimethyl-2,3,5,6-tetrahydrobenzo[a]phenanthridin-4(1H)-one, designated as compound 968, was discovered to be an allosteric inhibitor of GLS, and its inhibitory potential on cancer cell migration and proliferation have been reported." (PMID 34944392, 2021).
cancer (continued). "Therefore, successful strategies targeting the role of glutamate in cancers have focused on restricting glutamine metabolism via glutaminase inhibition." (PMID 34277440, 2021). "Indeed, preclinical data supports the combination of the glutaminase inhibitor, Telaglenastat (CB-839), in radiosensitization of cancer cells." (PMID 34733787, 2021). "These suggest that selective inhibition of glutamine metabolism (such as glutaminase or glutamine aminotransferase) might produce an anti-cancer effect." (PMID 35006438, 2021). "It was reported that N-terminal phosphorylation of glutaminase C (GAC) at serine 95 decreases its enzymatic activity and cancer cell migration while phosphorylation on GAC’s serine 314 catalyzed by PKCε leads to protein activation and an elevation of glutaminase activity and tumor malignancy." (PMID 34445210, 2021). "Given that most cancer cells are dependent on Gln metabolism for their growth and clinical grade GLS inhibitors are being developed to target this reliance on cancer cells, our findings may have more significant therapeutic implications." (PMID 34924566, 2021). "The glutaminase inhibitor could be killing specific cancer cell subgroups, leaving the treated tumors with less variation and tumor heterogeneity." (PMID 34564393, 2021). "In addition to the constitutive activation of Nrf2 by Keap1 deletion, DEM-induced Nrf2 activation was sufficient to sensitize cancer cells to glutaminase inhibition." (PMID 33672789, 2021). "In addition, the result was also consistent with our experimental result, that glutaminase expressed higher in cancer cells (AGS and MNK-45) than normal control cells (GES-1)." (PMID 34235071, 2021). "Similar metabolic perturbations and cell necrosis were evident in cancer tissue interfered by selenite in in vivo experiments, suggesting that selenite is also a potential therapeutic direction to affect lung carcinogenesis through targeting GLS." (PMID 35223460, 2021). "Some cancer cells actively import glutamine from extracellular fluids via glutamine transporter, whereas others prefer to synthesize glutamine from glutamate and ammonia by glutamine synthetase (GLS)." (PMID 35006438, 2021). "While preclinical and clinical studies have confirmed the sensitivity of TNBC to glutaminase inhibition, additional reports in a variety of cancer types have uncovered a set of intrinsic and extrinsic determinants that can impair cellular sensitivity to glutaminase inhibitors." (PMID 32450839, 2020). "Thus, diverse mechanisms of resistance are emerging as possible means for cancer cells to escape the effects of glutaminase inhibition." (PMID 32450839, 2020). "Therefore, Gln deprivation and GLS inhibition arrest cancer cells in S phase, while overexpression of GLS2 and exposure to differentiation agents elicit stop at G2/M phase." (PMID 32042057, 2020). "Moreover, several studies have demonstrated that inhibition of glutaminase increases the radiosensitivity and chemosensitivity of cancer." (PMID 32266129, 2020). "In contrast, Telaglenastat (CB-839) represents a potent, orally bioavailable GLS inhibitor showing anti-tumour activity in transplantable cancer models, including breast cancer and lymphoma, and ongoing clinical trials are examining efficacy in haematologic and solid cancers." (PMID 31980651, 2020). "It is noteworthy that CB-839 dependent glutaminase inhibition, in the genetic context of KEAP1 mutation, suppressed tumor growth in a panel of human cancer cells with different origin, while NRF2 activation by KI696 treatment sensitized KEAP1-WT cells previously refractory to CB-839." (PMID 32443774, 2020). "Inhibition of GLUL in CAFs, together with GLS inhibition in cancer cells, led to a synergistic effect in reducing tumour weight and metastasis in ovarian cancer mouse models when compared to monotherapy by disrupting the metabolic crosstalk between CAFs and ovarian tumour cells." (PMID 33092283, 2020).
cancer (continued). "Proposed strategies include depleting cancer cell glutamine supply, blocking glutamine uptake transporters, using glutamine mimetics as anti-metabolites, and the most promising, selective inhibition of GLS." (PMID 33092283, 2020). "Pharmacological inhibition of glutaminases gives different responses in various cancers, which may be due to the differential expression of glutaminase isoenzymes or emerge of alternative metabolic pathways." (PMID 33194749, 2020). "While these findings need to be confirmed in larger ongoing and future studies, it is reasonable to hypothesize the differential effects of GLS-1 inhibitors in cancer cells and immune cells." (PMID 32375310, 2020). "Cancers with high glutaminase expression are related to poor prognosis." (PMID 33510635, 2020). "Allosteric inhibitors of GLS (glutaminase) have shown promising results in cancer models." (PMID 33008042, 2020). "The regulation of GLS in cancer remains to be fully elucidated." (PMID 32937954, 2020). "In conclusion, we assume that GLS-1 contributes to SDHB-mutant malignant tumor growth and we presume that the evaluation of GLS-1 expression before therapy might yield valuable information for the management of the disease." (PMID 32150977, 2020). "Moreover, PTEN decreases the levels of pyruvate kinase isozyme M2 (PKM2) and 6- phosphofructo-1-kinase/fructose-2,6-biphosphatase isoform 3 (PFKFB3); and elicits the inhibition of the pro-tumorigenic glutaminase GLS1 thus contributing to the cancer-protection." (PMID 32211323, 2020). "All these findings suggested that the increase in glutamine metabolism mediated by ASCT2 and GLS might play an important role in the proliferation of cancer cells in OSCC lesions." (PMID 32162845, 2020). "The GLS1 gene encodes two isoforms, kidney-type glutaminase (KGA, long transcript isoform) and the glutaminase C (GAC, short transcript isoform), which are expressed in kidneys and in a variety of other tissues including cancer cells." (PMID 33016874, 2020). "The enzyme glutaminase converts glutamine to glutamate and is highly expressed in cancer cells." (PMID 32624705, 2020). "Indeed, metabolomic studies of an allosteric and reversible inhibitor of GLS, C.968, found that lipid catabolism is activated to compensate for inhibition of glutaminolysis in several cancer cells." (PMID 35582719, 2019). "Experimental trials have demonstrated that glutaminase-based molecular targeted therapy may lead to cancer cell apoptosis, thus preventing tumor development." (PMID 30871151, 2019). "While numerous approaches of targeting glutamine metabolism in cancer have been proposed and tested over the last several decades, inhibition of glutamine catabolism by glutaminase has emerged as a major focus of both academic and pharmaceutical cancer metabolism research." (PMID 31096630, 2019). "Inhibition of glutaminase has also shown pre-clinical activity as part of combination therapy in several tumor types, further expanding the potential impact that targeting glutaminase could have on cancer treatment." (PMID 31096630, 2019). "Both BAG3 and GLS are often highly expressed and play pro-survival activity in cancer cells." (PMID 30910998, 2019). "Glutamine, and hence glutaminase, have become appealing targets for cancer therapy." (PMID 30871151, 2019). "Thus, targeting glutaminase to disrupt vital metabolic pathways of tumors is considered to be a novel strategy to treat cancer." (PMID 31357507, 2019). "Inhibition of glutaminase has been stated as an attractive therapeutic approach in various cancers." (PMID 31088535, 2019). "Mechanistically, glutamate could be associated with cancers in terms of increased glutaminolysis (cancer cells dependency of extracellular glutamine) which through the action of glutaminase enzyme, converting glutamine to glutamate." (PMID 30893889, 2019).
cancer (continued). "Interestingly, the anti-cancer drug L-asparaginase harbors an intrinsic glutaminase activity and induces, through this glutaminase activity, a marked inhibition of mTORC1 and produces a pronounced apoptotic response in primary AML cells." (PMID 30813354, 2019). "Several small molecules that target GLS also have shown therapeutic potential for cancer patients." (PMID 31137815, 2019). "This systemic analysis eventually determined whether glutaminase expression can be used as a biomarker for the prognosis of human cancers." (PMID 30871151, 2019). "The expression of glutaminase is also up regulated in various cancer types." (PMID 30186229, 2018). "Glutaminase coverts glutamine into glutamate and is a promising target for anti-cancer therapy." (PMID 30151352, 2018). "Inhibition of glutaminase is therefore sought as an important goal for preventing cancer cell proliferation, or killing cancer cells since the addiction may indicate a cell survival mechanism." (PMID 29868609, 2018). "The concomitant use of GS and GLS inhibitors may represent a novel and lethal approach to target tumours and disrupt the metabolic crosstalk between stromal and cancer cells." (PMID 29967776, 2018). "To determine whether this regulatory mechanism is generally found in other cancer cell types, we treated lysates of different cancer cells with alkaline phosphatase, and then assessed glutaminase activity." (PMID 29515166, 2018). "Currently, glutaminase inhibitor is under clinical trial for testing anti-cancer efficacy." (PMID 28750681, 2017). "Thus, xCT/SLC7A11 expression, in conjunction with environmental cystine, is necessary and sufficient to increase glutamine catabolism, defining important determinants of glutamine anaplerosis and glutaminase dependence in cancer." (PMID 28826492, 2017). "Recently, GLS inhibitors are being examined as a new treatment for cancers." (PMID 28797105, 2017). "Asparagine synthetase (ASNS)-negative cancer types, which are defective in asparagine synthesis, are sensitive to L-asparaginase variants without glutaminase activity." (PMID 28750681, 2017). "Glutaminase is likely the rate-limiting enzyme for glutamine consumption in cancer cells and increased glutaminase activity by Rho GTPase through a NF-κB-dependent mechanism was described as a process involved in meeting the elevated glutamine demand in cancer cells." (PMID 28598356, 2017). "This upregulation of miR-141-3p and/or miR-200a-3p may have effects on several cancer-related target genes that have been previously associated with these two miRNAs, including E2F3, GLS, CCND2, PTEN, CCNG1, CDC25B, and ZFPM2." (PMID 28288173, 2017). "Proliferating cancer cells take up glutamine and convert it to glutamate through a variet of deamidation and transamidation reactions, most notably the mitochondrial amidohydrolase glutaminase." (PMID 28804274, 2017). "In addition, pharmacological “tool compound” inhibitors of LDH-A, GLS or lactate exporter MCT1 have been shown to inhibit MYC-dependent tumorigenesis in mouse models of cancer." (PMID 28443281, 2017). "According to the metabolic reprogramming of many types of cancer cells, glucose is mainly catabolized by aerobic glycolysis in tumors, while the fate of Glutamine is completed at mitochondrial level where the enzyme Glutaminase converts Glutamine to Glutamate." (PMID 29376023, 2017). "The GLS enzyme is reported to have a positive correlation with cancerous tumor growth from normal cells due to enhanced glutaminolysis, making it is a potential target for effective cancer therapeutic." (PMID 28446878, 2017).